FADS1 (fatty acid desaturase 1)
Diseases named in the same sentence as FADS1 in open-access papers (continued):
Sharing a sentence is not in itself a finding about the gene and the disease.
colorectal cancer (3 papers, 2021 to 2024). A primary or metastatic malignant neoplasm that affects the colon or rectum. "A genome-wide association study (GWAS) of colorectal cancer in East Asians has demonstrated that FADS1 expression in colon tumor tissues is higher than normal tissues." (PMID 34438249, 2021). "Through the TLR4/MYD88 pathway, Gram negative bacteria promote the induction of Delta-5 desaturase (FADS1), a rate-limiting enzyme for arachidonic acid synthesis from linoleic acid, which is upregulated in colorectal cancer." (PMID 38291460, 2024).
glioma (3 papers, 2020 to 2024). A benign or malignant brain and spinal cord tumor that arises from glial cells (astrocytes, oligodendrocytes, ependymal cells). "It was also shown that CD133+ glioma stem cells from in vitro cultured neurospheres display elevated FADS1 and FADS2 activities and that SCD and FADS2 exhibit spatial heterogeneity with higher expression in the peritumoral area." (PMID 36338708, 2022). "The enzymes required for essential fatty acid metabolism, fatty acid elongase 5 (ELOVL5), fatty acid desaturase 1 (FADS1) and fatty acid desaturase 2 (FADS2) are upregulated in low-grade glioma." (PMID 39251875, 2024). "Nevertheless, it seems that FADS1 and FADS2 in glioma tumors have anti-neoplastic properties." (PMID 32392704, 2020).
lipid metabolism disorder (3 papers, 2020 to 2025). "FADS1 (Fatty Acid Desaturase 1) is a protein-coding gene and associated with lipid metabolism disorder and mainly expressed in the liver, and catalyze the desaturation steps in the synthesis of n-3 and n-6 polyunsaturated fatty acids." (PMID 33339179, 2020). "This study identifies FADS1, FADS2, GLB1, and PNPLA3 as key genes integrating both lipid metabolism disorders and inflammation in MAFLD, with potential diagnostic implications." (PMID 41007773, 2025). "Moreover, KLF10-silenced groups exhibited overexpression of Cyb5r3, Fads1, and Fads2, which are involved in diseases such as lipid metabolism disorder." (PMID 34869587, 2021).
nutritional deficiency (3 papers, 2017 to 2021). "Nutritional deficiency and necrotic conditions also increased the expression of FADS1 2 times compared to B2M (p = 0.004) and 5 times compared to GAPDH (p = 0.004)." (PMID 32392704, 2020). "Furthermore, results of the recent studies suggest that the genes involved in hepatic lipid synthesis (ACACA, FASN, LPL, SCD1, FADS1, and FADS2) were down-regulated over nutritional deficiency." (PMID 35111749, 2021).
psoriasis (3 papers, 2024 to 2025). An autoimmune condition characterized by red, well-delineated plaques with silvery scales that are usually on the extensor surfaces and scalp. "In the GSE54456 dataset, APOE, CYP27A1, FADS1, and SOAT1 showed lower expression levels in psoriasis compared to the control group." (PMID 38273053, 2024). "In GSE66511 dataset, APOE, CYP27A1, FADS1, and SOAT1 were also significantly downregulated in psoriasis." (PMID 38273053, 2024). "Four hub genes APOE, CYP27A1, FADS1 and SOAT1 were downregulated in psoriasis, while were upregulated in leprosy." (PMID 38273053, 2024).
renal carcinoma (3 papers, 2022 to 2025). A carcinoma arising from the epithelium of the renal parenchyma or the renal pelvis. "In this study, we investigated the role and detailed molecular mechanism underlying FADS1 on controlling renal cancer cell proliferation and tumor growth." (PMID 40121894, 2025). "We found that pharmacological inhibition or knockdown of the expression of FADS1 significantly reduced the intracellular conversion of long-chain PUFAs, effectively inhibits renal cancer cell proliferation, and induces cell cycle arrest." (PMID 40121894, 2025). "Taken together, the inhibition of FADS1 in renal cancer cells promoted ER stress via activating the PERK/eIF2α/ATF4 pathway, with ATF3 likely playing a key role in mediating this effect." (PMID 40121894, 2025). "Our data provide new knowledge regarding the essential role of FADS1 in RCC, supporting FADS1 as new target for renal cancer." (PMID 40121894, 2025). "Our findings demonstrated that inhibiting FADS1 activity or knockdown of FADS1 expression can impede renal cancer cell proliferation and induce cell cycle arrest." (PMID 40121894, 2025). "In summary, our findings demonstrate that FADS1 inhibition effectively curtails renal cancer cell proliferation in vitro as well as tumor formation in vivo, primarily through the activation of the PERK-ATF4-ATF3 axis-mediated ER stress." (PMID 40121894, 2025). "As expected, FADS1-knockdown (FADS1-KD or sh-FADS1) significantly reduced the ratio of AA/DGLA in the renal cancer cell line 786-o." (PMID 38586033, 2024). "To further verify the impact of FADS1 inhibition on RCC cell proliferation and to elucidate the role of FADS1 in renal cancer cell growth, we employed FADS1-specific shRNA to knock down FADS1 expression in 786-o and A498 cells." (PMID 38586033, 2024). "In this study, we further investigated the role and downstream mechanism of action of FADS1 on renal cancer cell proliferation and tumorigenesis." (PMID 38586033, 2024). "Our studies hence collectively identify FADS1 as a key gene supporting the growth of renal cancer cells and as a therapeutic target for cancer treatment." (PMID 38586033, 2024). "We found that pharmacological inhibition or knockdown of the expression of FADS1 effectively inhibits renal cancer cell proliferation and induces cell cycle arrest." (PMID 38586033, 2024). "Collectively, these results indicate that FADS1 inhibition reduces renal cancer cell proliferation by inducing cell cycle arrest at the interphase stages preparing cell growth and DNA synthesis prior to cell mitosis." (PMID 38586033, 2024). "Our findings demonstrate that inhibiting FADS1 activity or knockdown of FADS1 expression can impede renal cancer cell proliferation and induce cell cycle arrest." (PMID 38586033, 2024). "Our study highlights FADS1-ER stress as a key therapeutic target for renal cancer, paving the way for novel drug discovery and development." (PMID 38586033, 2024). "Taken together, inhibition of FADS1 in renal cancer cells promoted ER stress, with the likelihood that the ATF family of genes, especially ATF3, plays a key role in mediating this effect." (PMID 38586033, 2024). "In summary, our findings demonstrate that FADS1 inhibition effectively curtails renal cancer cell proliferation in vitro as well as tumor formation in vivo, primarily through the activation of the ATF3 axis-mediated ER stress." (PMID 38586033, 2024). "Taken together, our analyses suggested that increased FADS1 expression is associated with worse survival among patients with non-brain cancers, particularly renal cancers, but is associated with better survival among those with brain cancers." (PMID 36046053, 2022). "Our data provide new knowledge regarding the essential role of FADS1 in RCC and demonstrates the therapeutic potential of targeting FADS1 for renal cancer." (PMID 38586033, 2024).
renal carcinoma (continued). "Treatment with D5D-IN-326 significantly inhibits the conversion of dihomo-γ-linolenic acid (DGLA), the direct substrate of FADS1, into arachidonic acid (AA), as indicated by the reduced AA/DLGA ratio in the renal cancer cell line 786-o." (PMID 38586033, 2024). "Treatment with D5D-IN-326 significantly inhibits the conversion of dihomo-γ-linolenic acid (DGLA), the direct substrate of FADS1, into arachidonic acid (AA), as indicated by the reduced AA/DLGA ratio in the renal cancer cell line 786-o and A498 at 48 h and 96 h." (PMID 40121894, 2025).
adenoma (2 papers, 2015 to 2018). A neoplasm arising from the epithelium. "Two more genes had increased expression in carcinoma compared to adenoma, and these are FADS1 and G0S2." (PMID 30175151, 2018). "No significant gene expression alterations could be detected in the stromal cells isolated from adenomas compared to the normals, but COL1A2, FADS1, MAL, PRIMA1, SULF1, THBS2, TIMP1 genes’ transcripts showed significant differences (p < 0.05) in logFc values for the tumour versus normal comparison." (PMID 26482433, 2015). "In addition, ALDH1A3, COL1A2, FADS1, SFRP2, SULF1, and THBS2 were found to be significantly (p < 0.01) differentially expressed in tumour samples but not in adenomas compared to healthy samples." (PMID 26482433, 2015).
brain cancer (2 papers, 2022 to 2023). A primary or metastatic malignant neoplasm affecting the brain. "Studies have shown that the expression of FADS1 increases in brain cancers of primary tumors, and the underlying mechanism for FADS1-mediated tumor progression is that FADS1 affects the cholesterol synthesis process and cell cycle arrest 58-60." (PMID 37325064, 2023). "Particularly, increased FADS1 expression is positively associated with tumor formation (primary tumor) and cancer progression (recurrent tumor) among non-brain cancers and negatively associated with cancer progression (recurrent tumor) in brain cancers." (PMID 36046053, 2022). "Genes whose mRNA levels are correlated with that of FADS1 in all cancers and non-brain cancers mainly belong to two categories: lipid metabolism and DNA damage response." (PMID 36046053, 2022). "The genes correlated with FADS1 with Spearman’s correlation coefficient ≥0.3 or ≤ -0.3 (P <0.05) in each cancer type, brain cancers, non-brain cancers and in all cancers as a whole were used for further pathway enrichment analysis." (PMID 36046053, 2022). "The common genes co-expressed with FADS1 among brain cancers exclusively belong to lipid metabolism." (PMID 36046053, 2022). "Notably, when the samples are analyzed for just brain cancers we found that higher expression of FADS1 is observed in primary tumor compared to recurrent tumors." (PMID 36046053, 2022). "Also, the in vitro assay demonstrated that RCC cells and brain cancer cells are sensitive and resistant to FADS1 inhibitor, respectively." (PMID 36046053, 2022). "Meanwhile, pharmacological inhibiting FADS1 activity also demonstrated a dose-dependent response among non-brain cancer cells, and not in non-cancerous cells, suggesting that FADS1 is a potential novel target for anti-cancer treatment." (PMID 36046053, 2022). "Moreover, correlations among non-brain and all cancers are mostly bidirectional but for brain cancers some of the top pathways e.g., Cell cycle control of chromosomal replication and Role of CHK proteins in cell cycle checkpoint control are only positively correlated with FADS1 in brain cancers." (PMID 36046053, 2022).
colon adenocarcinoma (2 papers, 2022 to 2025). "The FADS1/2 genes are also overexpressed in colon adenocarcinomas, further emphasising the role of the FADS genes in CRC risk." (PMID 40897820, 2025).
Hypercholesterolemia (2 papers, 2017 to 2024). An increased concentration of cholesterol in the blood. "The expression of mRNAs of FADS1 (Δ5-desaturase) and FADS2 (Δ6-desaturase) significantly decreased in the liver due to isolated hypercholesterolemia." (PMID 28750643, 2017).
hypopharyngeal carcinoma (2 papers, 2023 to 2024). Carcinoma, predominantly squamous cell, arising from the epithelial cells of the hypopharynx. "FADS1 expression was elevated in hypopharyngeal carcinoma tissues compared to adjacent normal tissues." (PMID 37325064, 2023). "LINC01569 downregulation restrains macrophages from polarizing toward M2 through the miR-193a-5p/FADS1 signaling axis, thereby helping tumor cells escape inherent immune surveillance and promoting the occurrence and development of hypopharyngeal carcinoma." (PMID 37325064, 2023). "Our findings revealed that LINC01569 regulates macrophage polarization, resulting in the occurrence and development of hypopharyngeal carcinoma through the miR-193a-5p/FADS1 signaling axis." (PMID 37325064, 2023). "In the in vivo study, LINC01569 knockdown in macrophages inhibited tumor growth and cell viability of hypopharyngeal cancer cells, which were reversed by the miR-193a-5p inhibitor and restored by FADS1 knockdown." (PMID 37325064, 2023). "Importantly, miR-193a-5p expression negatively correlated with FADS1 expression in hypopharyngeal carcinoma." (PMID 37325064, 2023). "Therefore, activation of the LINC01569/miR-193a-5p/FADS1 signaling axis in macrophages can accelerate M2 macrophage polarization, thereby leading to the progression of hypopharyngeal cancer." (PMID 37325064, 2023). "In this study, we revealed that LINC01569 was upregulated in the tumor macrophages of hypopharyngeal carcinoma and promoted the occurrence of hypopharyngeal carcinoma through the LINC01569/miR-193a-5p/FADS1 axis." (PMID 37325064, 2023).
laryngeal carcinoma (2 papers, 2020 to 2024). Carcinoma that arises from the laryngeal epithelium. "We also found that FADS1 variation was significantly associated with laryngeal cancer risk by genome-wide association study (GWAS), combined with GEPIA analysis and experimental data." (PMID 32332698, 2020). "We manipulated FADS1 expression in TU212 cells by lentivirus transfection to observe FADS1 bioactivity, after assessing FADS1 levels in laryngeal carcinoma cell lines (AMC-HN-8, TU212, TU686)." (PMID 32332698, 2020). "Therefore, in this study, we performed in vitro and in vivo assays, and identified that FADS1, as a main mediator of PUFAs, played an oncogenic role in the progression of laryngeal cancer by activating the AKT/mTOR signaling." (PMID 32332698, 2020). "Thus, our results demonstrated that FADS1 downregulation could suppress the viability of laryngeal cancer cells by reducing cell proliferation, promoting cell apoptosis and senescence." (PMID 32332698, 2020). "However, the molecular mechanism of FADS1 in laryngeal cancer still remain to be elucidated." (PMID 32332698, 2020). "Previous research has shown that Fatty Acid Desaturase 1 (FADS1), a rate-limiting enzyme in LC-PUFA bioproduction, plays a significant role in the growth of various cancer cells and is overexpressed in colon, pancreas, breast, and laryngeal cancers." (PMID 38586033, 2024).
melanoma (2 papers, 2017 to 2023). A malignant, usually aggressive tumor composed of atypical, neoplastic melanocytes. "As mentioned, we noticed a lower level of mRNA of SC4MOL (implicated in cholesterol biosynthesis), FADS1, and FASN in adipocytes cocultured with melanoma cells." (PMID 37481560, 2023).
non-small cell lung carcinoma (2 papers, 2020 to 2021). A group of at least three distinct histological types of lung cancer, including non-small cell squamous cell carcinoma, adenocarcinoma, and large cell carcinoma. "In other types of tumors, FADS1 and FADS2 exhibit oncogenic properties, for example in non-small-cell lung cancer, where the lower expression of FADS1 is associated with worse prognosis." (PMID 32392704, 2020).
oral cancer (2 papers, 2017 to 2025). "The study found a significant interaction between the FADS1 gene and fish intake in relation to oral cancer risk." (PMID 40430008, 2025). "After adjustment for potential confounders, FADS1 A variant allele was associated with a significantly decreased risk of oral cancer: the ORs were 0.65 (95% CI: 0.42-0.99) for codominant model and 0.67 (95% CI: 0.46-0.98) for recessive model." (PMID 28178666, 2017). "In conclusion, our results suggest that FADS1 rs174549 polymorphism showed a protective role in etiology of oral cancer." (PMID 28178666, 2017). "Interestingly, our results demonstrated a significant gene-diet interaction between FADS1 gene and fish intake for oral cancer risk." (PMID 28178666, 2017). "Furthermore, a significant gene-diet multiplicative interaction was observed between FADS1 rs174549 polymorphism and fish intake for oral cancer (P=0.028)." (PMID 28178666, 2017). "However, so far, there is limited epidemiologic research on the role of FADS1 gene polymorphism in oral cancer risk." (PMID 28178666, 2017). "This preliminary study suggests that FADS1 rs174549 polymorphism and fish consumption may be protective factors for oral cancer, with a gene-diet multiplicative interaction." (PMID 28178666, 2017). "Moreover, it is still unclear whether FADS1 gene polymorphism and its interaction with fish intake could contribute to the prevention of oral cancer risk." (PMID 28178666, 2017). "Therefore, we speculated that imbalance between AA and EPA and DHA might be a mechanism of FADS1 rs174549 polymorphism on oral cancer." (PMID 28178666, 2017). "The aim of this study was to investigate the independent and combined effects of fatty acid desaturase 1 (FADS1) gene polymorphism and fish consumption on oral cancer." (PMID 28178666, 2017). "Furthermore, there was a positive multiplicative interaction between FADS1 gene and fish intake for oral cancer." (PMID 28178666, 2017). "Moreover, a positive multiplicative interaction between FADS1 gene and fish intake for oral cancer was found (ORmultiplicative = 0.70, 95% CI: 0.51-0.96, P=0.028; data not shown)." (PMID 28178666, 2017). "Although the mechanism of rs174549 polymorphism on oral cancer is not clear, previous study found there were 49 SNPs in high linkage disequilibrium with rs174549 in the same chromosome, and these SNPs might influence the expression of FADS1 through their effects on host genes." (PMID 28178666, 2017).
ovarian carcinoma (2 papers, 2018 to 2023). A malignant neoplasm originating from the surface ovarian epithelium. "SCD1 and FASN expressions were higher and ELOVL1–6 and FADS1 expressions were lower in ovarian cancer tissue, while ACC1 and FADS2 were unchanged." (PMID 37712874, 2023). "To determine whether fatty acid metabolism is altered in ovarian cancer tissue, we first evaluated the gene expression of fatty acid synthases (ACC1, FASN), fatty acid desaturases (SCD1, FADS1, FADS2) and fatty acid elongase 1–6 (ELOVL1–6) in ovarian tumor tissues and normal ovarian tissues." (PMID 37712874, 2023).
pancreatic cancer (2 papers, 2020 to 2025). "Genetic variations—particularly single-nucleotide polymorphisms (SNPs) in the FADS1 and FADS2 genes—affect PUFA metabolism, linking circulating PUFA levels to the risk of several cancers, including breast, colorectal, prostate, and pancreatic cancers." (PMID 40430008, 2025).